PTHLH (parathyroid hormone like hormone)
Diseases named in the same sentence as PTHLH in open-access papers (continued):
Sharing a sentence is not in itself a finding about the gene and the disease.
lung carcinoma (46 papers, 2002 to 2026). "Emodin inhibits transcription Factor 4 (TCF4)- Twist family bHLH transcription factor 1 (TWIST1) complex formation, thereby suppressing parathyroid hormone-like hormone (PTHLH) protein expression, which are implicated in lung cancer cachexia." (PMID 40490812, 2025). "Consistent with the findings of previous studies, this study demonstrated that the expression of PTHLH was upregulated in response to TGFβ1 signalling in various lung cancer cell lines." (PMID 35406121, 2022). "In this study, the expression levels of PTHLH mRNA in patients with lung cancer were investigated using publicly available gene expression datasets." (PMID 35406121, 2022). "Here, we found that FOXA1 knockdown decreased CDH1 (epithelial marker) but increased CDH2, VIM, SNAI2, and PTHLH (mesenchymal markers) in A549 lung cancer cells." (PMID 35897813, 2022). "The interaction between TCF4 and TWIST1 upregulated PTHLH expression in lung cancer cells in response to TGFβ1 stimulation." (PMID 35406121, 2022). "In this study, the interaction between TCF4 and TWIST1 upregulated PTHLH expression and consequently promoted lung cancer growth and cachexia." (PMID 35406121, 2022). "In this study, Pc-Ex, which contains emodin as a major component, sufficiently suppressed the PTHLH mRNA and PTHrP expression levels in lung cancer cells stimulated with TGFβ1 by inhibiting the interaction between TCF4 and TWIST1." (PMID 35406121, 2022). "Through bioinformatic analysis of the GSE114761 dataset increased PTHLH mRNA levels were found in TGFβ1-treated many types of lung cancer cells." (PMID 35406121, 2022). "The interaction between TCF4 and TWIST1 promotes lung cancer growth, metastasis, and cachexia by upregulating the expression of PTHLH and EMT-related genes." (PMID 35406121, 2022). "The PTHLH mRNA levels were upregulated in lung cancer cells ectopically overexpressing Myc-TCF4." (PMID 35406121, 2022). "This suggests that PTHLH is a critical component for TGFβ1-induced cachexia in lung cancer." (PMID 35406121, 2022). "In addition, ectopic FOXA1 expression significantly reversed TGFβ1-mediated expression of EMT markers, such as CDH1, CDH2, VIM, SNAI2, and PTHLH, in A549 lung cancer cells." (PMID 35897813, 2022). "The expression of PTHLH is upregulated in TGFβ1-treated breast and lung cancer cells." (PMID 35406121, 2022). "Conversely, TCF4 knockdown downregulated PTHLH expression in lung cancer cells." (PMID 35406121, 2022). "The PTHLH mRNA levels were upregulated upon TCF4 overexpression and downregulated upon TCF4 silencing in lung cancer cells." (PMID 35406121, 2022). "Consistent with the findings of previous studies, the expression of PTHLH was significantly upregulated in TGFβ1-treated A549, NCI-H1299, NCI-H1650, NCI-H358, L132, Calu-1, and Calu-3 lung cancer cells." (PMID 35406121, 2022). "Bioinformatic analysis of GSE74706 and GSE22863 datasets revealed that the PTHLH mRNA levels were upregulated in non-small cell lung cancer (NSCLC) and primary lung cancer." (PMID 35406121, 2022). "TGFβ1-induced PTHLH expression was mitigated in TCF4-silenced A549 and Calu-1 lung cancer cells." (PMID 35406121, 2022).
breast tumor (25 papers, 1997 to 2025). "Interestingly, PTHLH has also been implicated in breast tumor metastasis to bone in a mouse model." (PMID 22087758, 2011).
bone metastasis (23 papers, 2002 to 2026). Transfer of a neoplasm from its primary site to bones. "A panel of cytokines including interleukin 1 (IL1), interleukin 6 (IL6), parathyroid hormone like hormone (PTHrP) and colony-stimulating factor 1 (CSF-1) can induce the activation of osteoclasts in bone metastasis." (PMID 35685372, 2022).
Cachexia (21 papers, 2017 to 2026). Severe weight loss, wasting of muscle, loss of appetite, and general debility related to a chronic disease. "Here we show that PTHrP, which is encoded by the HIF2-responsive gene PTHLH, is a critical driver of two paraneoplastic syndromes in ccRCC: cachexia and humoral hypercalcemia." (PMID 41315757, 2026). "We next performed loss-of-function and gain-of-function PTHLH studies to ask whether PTHrP was necessary or sufficient, respectively, for the rapid induction of cachexia by OSRC-2 cells." (PMID 41315757, 2026). "Here we show that the PTHrP, which is encoded by the HIF2-responsive gene PTHLH, is a critical driver of two paraneoplastic syndromes in ccRCC: cachexia and humoral hypercalcemia." (PMID 40964365, 2025). "This indicated that emodin exerts potential therapeutic effects on cachexia by downregulating the expression of PTHLH and EMT-related genes." (PMID 35406121, 2022).
colon carcinoma (17 papers, 1997 to 2025). "Our study provides an explanation as to why PTHLH is upregulated in colon cancer; however, further studies are required to extend our findings to other models of cancers." (PMID 30115896, 2018). "PTHLH is up-regulated in oral squamous cell carcinoma (OSCC), head and neck squamous cell carcinoma (HNSCC), colon cancer, and hepatocellular carcinoma (HCC)." (PMID 34301206, 2021). "The current study demonstrated that in colon cancer, TADC-derived CXCL1 promotes expression of high levels of the PTHLH transcript and its protein, which are negatively correlated with relapse-free and overall survival rates in colon cancer." (PMID 30115896, 2018). "TGF-β-dependent signaling activates PTHLH expression by increasing transcription from the P3 promoter through a synergistic interaction of the transcription factors Smad3 and Ets1, and p38 MAPK-dependent signaling controls PTHLH expression in metastatic colon cancer cells." (PMID 31487323, 2019).
osteosarcoma (17 papers, 2011 to 2026). A usually aggressive malignant bone-forming mesenchymal neoplasm, predominantly affecting adolescents and young adults.
squamous cell carcinoma (15 papers, 2007 to 2026). A carcinoma arising from squamous epithelial cells. "After grouping the needle and tumor biopsy array data by tumor type we confirmed that PTHLH was indeed induced, most strongly in the squamous cell carcinoma tissues." (PMID 19662208, 2007).
renal cell carcinoma (14 papers, 2008 to 2026). "Intracrine actions of PTHLH in cancer cells have been associated with increased resistance to apoptosis and anchorage‐independent growth in human renal cell carcinoma via PI3K/Akt." (PMID 31293052, 2019). "High serum calcium (Ca) due to aberrant secretion of tumor parathyroid hormone-like hormone (PTHLH) is a well-known paraneoplastic sign and is associated with poor prognosis in patients with renal cell carcinoma (RCC)." (PMID 24861371, 2014).
pancreatic cancer (12 papers, 2015 to 2026). "In pancreatic cancer, the protein named PTHrP (encoded by PTHLH) can drive the growth of primary and metastatic tumors in mice." (PMID 36439109, 2022). "Given our findings that BRDT colocalized with ΔNp63 on several genes such as FAT2 and PTHLH, which we previously demonstrated as being associated with ΔNp63-dependent SEs in pancreatic cancer, we investigated whether BRDT, like BRD4, may be a defining feature of SEs in a subset of ESCC." (PMID 33658703, 2021). "Also, it was reported that a subset of human pancreatic carcinomas showed copy number gains of PTHrP (encoded by PTHLH gene), as part of KRAS amplification, which is frequent in pancreatic carcinomas." (PMID 37540958, 2023). "Moreover, and in agreement with our results, PTHLH acts a prosurvival factor in pancreatic cancer cells that up‐regulates c‐myc and increases the ratio of anti‐apoptotic to pro‐apoptotic members of the Bcl2 family." (PMID 31293052, 2019).
melanoma (11 papers, 2011 to 2025). A malignant, usually aggressive tumor composed of atypical, neoplastic melanocytes. "Also and in line with our data, PTHLH inactivation in human melanoma cells impaired cell motility, invasion, anchorage‐independent growth and reduced their metastatic behavior." (PMID 31293052, 2019).
colorectal cancer (8 papers, 2017 to 2026). A primary or metastatic malignant neoplasm that affects the colon or rectum. "CXCL1 may also facilitate the formation of metastasis by inducing an increase in parathyroid hormone-like hormone (PTHLH) expression in colorectal cancer cells —a factor that causes bone remodeling during the formation of bone metastasis." (PMID 37408240, 2023). "The inactivation or downregulation of p38MAPK signalling is reported to suppress PTHLH expression in lung and liver metastases of primary colorectal cancer." (PMID 35406121, 2022).
Hypocalcemia (8 papers, 2014 to 2025). An abnormally decreased calcium concentration in the blood. "It is postulated that 5-HT induces transient hypocalcemia, stimulating the negative feedback loop and resulting in increased PTHLH synthesis to restore blood Ca concentrations." (PMID 39650027, 2024).
oral cancer (8 papers, 2006 to 2023). "Overall, the passage highlights the potential diagnostic value of IL-8, IL-6, and TNF-α as biomarkers for oral cancer and the upregulation of PTHLH/PTHrP in various tumors, including OSCC." (PMID 38067304, 2023). "Studies showed that PTHLH is highly expressed in oral cancer and tongue cancer." (PMID 37555363, 2023).
brachydactyly type E (7 papers, 2014 to 2026). Brachydactyly type E (BDE) is a congenital malformation of the digits characterized by variable shortening of the metacarpals with more or less normal length phalanges, although the terminal phalanges are often short. "Another connection between human genetic bone disorder and PTHrP signaling is shown in brachydactyly type E, caused by loss-of-function mutations in parathyroid hormone-like hormone (PTHLH), a PTHR1 ligand, and characterized by bone shortening of hands and feet." (PMID 33919228, 2021). "One exception is the parathyroid hormone-like hormone gene (PTHLH, *168470), which is clearly associated with brachydactyly type E2 (MIM #613382), inherited in an autosomal dominant manner." (PMID 41595523, 2026). "Mutations in PTHLH (PTH-like hormone), cause brachydactyly type E (BDE) characterized by shortening of metacarpals, metatarsals and/or phalanges with short stature." (PMID 37501674, 2023). "The mechanistic connection between PTHrP and HDAC4 also help explain why HDAC4 haploinsufficiency causes Brachydactyly mental retardation syndrome, which is phenotypically similar to Brachydactyly type E caused by mutations in PTHLH, the gene that encodes PTHrP." (PMID 38370361, 2024).
head and neck cancer (7 papers, 2009 to 2026). A primary or metastatic malignant neoplasm affecting the head and neck. "We observed that PTHLH expression in the head and neck cancer cell line SCC-9 was induced by hypoxia." (PMID 40964365, 2025). "The database shows that the ITGA6 and PTHLH are highly relevant to head and neck cancer, which are specifically expressed in the tissue." (PMID 37555363, 2023). "In this study, we investigated the role of PTHLH in head and neck cancer by analyzing its expression in clinical patients and its phenotypic impact by investigating in vitro and in vivo cell growth due to PTHLH in HNSCC." (PMID 28120940, 2017). "Promising markers for head and neck cancers include parathyroid hormone-like hormone (PTHLH, also known as PTHrP), serpin peptidase inhibitor, clade B (ovalbumin), member 3 (SERPINB, also known as SCCA), and lymphocyte antigen 6 complex, locus D (LY6D, also known as E48)." (PMID 19961621, 2009). "Some of these genes are even associated with a characteristic role in the tumorigenesis of head and neck carcinoma (like SOX2, CRYAB, and PTHLH)." (PMID 37455825, 2023). "PTHLH expression is controlled by RUNX2 and is correlated with head and neck cancer growth." (PMID 28120940, 2017). "We speculate that PTHLH could be a biomarker for HNSCC progression and may be a potential therapeutic target for head and neck cancer patients." (PMID 28120940, 2017).
head and neck squamous cell carcinoma (7 papers, 2014 to 2026). A squamous cell carcinoma that arises from any of the following anatomic sites: lip and oral cavity, nasal cavity, paranasal sinuses, pharynx, larynx, and salivary glands. "The Runx2-mediated activation of PTHLH expression promotes the growth of head and neck squamous cell carcinoma." (PMID 35406121, 2022). "Parathyroid Hormone-Like Hormone (PTHLH) is an autocrine/paracrine ligand that is up-regulated in head and neck squamous cell carcinoma (HNSCC)." (PMID 28120940, 2017).
oral squamous cell carcinoma (7 papers, 2011 to 2022). "In our previous study, parathyroid hormone-like hormone (PTHLH) which encodes parathyroid hormone-related protein (PTHrP) was revealed to be up-regulated in oral squamous cell carcinoma (OSCC) compared with paired apparently normal surgical margins using microarray method." (PMID 25539663, 2014).
Osteochondroma (7 papers, 2008 to 2023). A common, benign cartiliginous neoplasm arising from the metaphysis of bone. "In the growth plate, IHH regulates chondrocyte proliferation and differentiation in a tightly regulated paracrine feedback loop, together with PTHLH, and deregulated IHH signaling has been implicated in the pathogenesis of osteochondromas." (PMID 21403832, 2011). "Upregulation of PTHLH and Bcl-2 characterizes malignant transformation of osteochondroma." (PMID 21403832, 2011). "PTHLH signalling, which is downstream of IHH and is responsible for chondrocyte proliferation, is absent in osteochondroma, while being upregulated upon malignant transformation of osteochondroma." (PMID 18271966, 2008). "IHH/PTHLH and FGF signaling molecules are mostly absent in osteochondromas and reexpressed with the progression of osteochondroma towards peripheral CHSs." (PMID 21403832, 2011).
squamous cell lung carcinoma (7 papers, 2011 to 2026). A carcinoma arising from squamous bronchial epithelial cells. "In this regard, our pan-cancer analyses suggest that PTHLH is significantly correlated with HIF transcriptional activity in multiple cancer types, including HNSC and lung squamous cell carcinoma." (PMID 41315757, 2026).
hepatocellular carcinoma (5 papers, 2012 to 2021). A malignant tumor that arises from hepatocytes. "PTHLH is one of our identified significant high expression (fold change ≥2) genes in human hepatocellular carcinoma (HCC) compared with low expression no-tumor hepatitis/cirrhotic tissues (HBV or HCV infection) from GEO data set GSE10140-10141." (PMID 22997493, 2012).
neuroblastoma (5 papers, 2015 to 2024). Neuroblastoma (NB) is the most common solid, extracranial childhood tumor. "Our previous results indicate that PTHLH plays an important role in the biology and pathogenesis of neuroblastoma." (PMID 31293052, 2019). "In accordance with this result, canertinib reduced PTHLH mRNA expression levels in all neuroblastoma cells analyzed as well." (PMID 31293052, 2019). "Given that our results indicated that their expression is necessary for neuroblastoma cell invasion and that PTHLH knockdown reduces MYCN expression, we sought to identify the mechanism responsible for PTHLH production in neuroblastoma." (PMID 31293052, 2019). "Taking into account the therapeutic potential of reducing PTHLH expression in malignant neuroblastomas, we sought to identify the molecule/s that control its production specifically in this tumoral context, as this would provide a therapeutic opportunity." (PMID 31293052, 2019). "We previously hypothesized that epidermal growth factor (EGF), the main regulator of PTHLH in several cancer types, might control PTHLH in neuroblastoma as well." (PMID 31293052, 2019). "Moreover, the identification of EGFR as a transcriptional regulator of PTHLH in neuroblastoma provides a novel therapeutic opportunity to promote a less aggressive tumor phenotype through irreversible inhibition of EGFR tyrosine kinase activity." (PMID 31293052, 2019). "In order to get further insights into the role of PTHLH in the tumorigenicity of neuroblastoma, we explored whether stable knockdown of PTHLH expression affects the invasive and migratory capacities of those cells." (PMID 31293052, 2019). "Conversely, we here show that PTHLH is controlled by EGFR in neuroblastoma." (PMID 31293052, 2019). "Given that CaSR has been shown to stimulate PTHLH production in other cellular contexts, we initially assessed whether this was also the case in neuroblastoma." (PMID 31293052, 2019). "In neuroblastoma, as our migration assays showed, PTHLH can both promote and inhibit migration depending on whether it acts through its receptor or not." (PMID 31293052, 2019). "This study provides the first evidence of the dual role of PTHLH in the behavior of neuroblastomas." (PMID 31293052, 2019). "We here show that PTHLH and its receptor PTH1R play a role in neuroblastoma cell migration and invasion." (PMID 31293052, 2019). "Stable knockdown of PTHLH and PTH1R was conducted in neuroblastoma cell lines to investigate the succeeding phenotype induced both in vitro and in vivo." (PMID 31293052, 2019). "All these data considered, the aim of this work was to functionally analyze the role of PTHLH and its receptor, PTH1R, in neuroblastoma." (PMID 31293052, 2019). "All these data together reinforce the idea of an oncogenic; intracrine role of PTHLH is acting in more aggressive neuroblastomas, whereas a PTH1R‐dependent, paracrine role of PTHLH would be predominant in good prognosis primary tumors." (PMID 31293052, 2019). "We here investigate the role of PTHLH and PTH1R in neuroblastoma and show their contribution to neuroblastoma behavior, both benign and malignant." (PMID 31293052, 2019).
neuroblastoma (continued). "The aim of this study was to functionally assess the role of PTHLH and its receptor, PTH1R, in neuroblastoma." (PMID 31293052, 2019). "We also show that PTHLH expression is not under the control of the calcium‐sensing receptor in neuroblastoma." (PMID 31293052, 2019). "As expected based on our previous reports, PTHLH was not under the control of the CaSR in neuroblastoma." (PMID 31293052, 2019). "Acute CaSR activation did not induce PTHLH upregulation in neuroblastoma cell lines exhibiting endogenous CaSR expression." (PMID 31293052, 2019). "Therefore, given that we have unveiled the factor mainly responsible for PTHLH production in this tumoral context, it might be of therapeutic interest since it is feasible to reduce PTHLH production specifically in malignant neuroblastomas without damaging normal tissues." (PMID 31293052, 2019). "Since a profound PTHLH downregulation was not achieved, presumably because it compromises neuroblastoma cell viability, and to further validate MYCN downregulation upon PTHLH silencing, LA‐N‐1 cells were transiently transfected with PTHLH small interfering RNA (siRNA)." (PMID 31293052, 2019).